GSK3B (glycogen synthase kinase 3 beta)
Diseases named in the same sentence as GSK3B in open-access papers (continued):
Sharing a sentence is not in itself a finding about the gene and the disease.
Myocardial fibrosis (14 papers, 2019 to 2024). "ACP5 influences the proliferation, migration, and phenotypic transition of CFs via modulating the ERK/GSK3β/β-catenin signaling pathway, leading to the development of myocardial fibrosis after MI." (PMID 38879488, 2024). "BPS improved myocardial fibrosis and upregulated GSK‐3β protein expression in male SD rats after the operation." (PMID 38018586, 2023). "BPS treatment increased the binding of YBX1 to the GSK‐3β promoter, and GSK‐3β protein expression was upregulated, which further caused the upregulation of p‐CREB and cAMP, and finally inhibited myocardial fibrosis." (PMID 38018586, 2023). "After operation, BPS improved myocardial fibrosis and upregulated GSK‐3β protein expression in male SD rats." (PMID 38018586, 2023). "GSK‐3β knockdown in fibroblasts can aggravate myocardial fibrosis and adverse ventricular remodeling after MI, and GSK‐3β deletion in cardiomyocytes leads to ventricular obstruction in mice." (PMID 38018586, 2023). "NFκB signaling pathway has been found activated in ACM and is closely linked to GSK3β signaling, which promoted TGF-β1 expression and enhanced its downstream signaling, leading to myocardial fibrosis." (PMID 35845067, 2022). "It has been reported that 2,5-dimethylcelecoxib (DM-celecoxib) can inhibit myocardial fibrosis in mice with dilated cardiomyopathy by activating GSK-3β, which contributes to prolonged lifespan." (PMID 33052244, 2020). "This action is reversed by the transfection of GSK-3β overexpression vector, suggesting that GSK-3β is a vital mediator for myocardial fibrosis." (PMID 33052244, 2020). "Constitutively active GSK-3β prevents pathological hypertrophy in transgenic mice, which seems to be beneficial for the protection of myocardial fibrosis." (PMID 33052244, 2020). "Our team also demonstrated that inhibiting AKT/GSK3β attenuated pressure overload‐induced myocardial fibrosis and blocked cardiac fibroblasts activation and transformation in vitro." (PMID 30741414, 2019). "ACP5 may influence the proliferation, migration, and phenotypic transition of CFs, leading to the development of myocardial fibrosis after MI through modulating the ERK/GSK3β/β-catenin signaling pathway." (PMID 38879488, 2024). "This is the first study to propose that ACP5 may promote myocardial fibrosis after MI through the regulation of the ERK/GSK3β/β-catenin pathway." (PMID 38879488, 2024). "However, the molecular mechanism of how BPS regulates GSK‐3β expression in myocardial fibrosis is worth further investigation." (PMID 38018586, 2023). "We next investigated whether BPS acts on myocardial fibrosis through YBX1/GSK‐3β ultimately affecting cAMP signaling pathway." (PMID 38018586, 2023). "Moreover, it has been reported that miR-154-induced GSK-3β inhibition promotes myocardial fibrosis in human cardiac fibroblasts from 51 patients with cardiomyopathy." (PMID 33052244, 2020). "The experimental results may suggest that GSK-3β has a protective effect on myocardial fibrosis in a HFD setting." (PMID 33052244, 2020). "Targeting SOX9 in fibroblasts could improve myocardial fibrosis by regulating AKT/GSK-3β/β-catenin." (PMID 35586685, 2022).
COVID-19 (13 papers, 2020 to 2025). A disease caused by infection with severe acute respiratory syndrome coronavirus 2. "GSK3β inhibition prompts the acquisition of the transcriptional profile of severe COVID-19 pathogenic pulmonary macrophages via MAFB." (PMID 37917179, 2023). "Increased IFN-γ in the plasma of recovered Wuhan COVID-19 patients contributed to PD-1 downregulation on CD8+ T cells by regulating the AKT/GSK3β signaling pathway." (PMID 38424104, 2024). "Through network analysis, it was found that the core targets of GGQL in the treatment of COVID-19 comorbid with DM include AR, GSK3B, DPP4, F2, NOS3, and so on." (PMID 37933071, 2023). "Together, the high ratio of potential hits and relatively low toxicity of the library as a whole support the viability of GSK3β as a target for HDT in COVID-19 and other human coronaviruses infections." (PMID 36508083, 2022). "Research indicates that targeting GSK3B might offer a dual benefit in COVID-19 treatment by inhibiting viral replication and boosting the immune response." (PMID 40919176, 2025). "scRNA-seq bioinformatics analysis revealed that AKT/GSK3β may regulate the INF-γ/PD-1 axis in CD8+ T cells from COVID-19 convalescent patients." (PMID 38424104, 2024). "Given the overexpression of MAFB-dependent genes in severe COVID-19 pathogenic macrophages, we next assessed the effect of the pharmacological upregulation of MAFB (using the GSK3β inhibitor CHIR99021) on the gene sets that define pathogenic macrophages in severe COVID-19." (PMID 37917179, 2023). "Thus, pharmacological inhibition of GSK3β increases MAFB expression and reprograms macrophages toward enhanced expression of the gene signatures of macrophages associated to COVID-19 severity." (PMID 37917179, 2023). "Combined with single-cell RNA-seq (scRNA-seq) bioinformatics and flow cytometry, we further demonstrated that the AKT/GSK3β signaling pathway may be involved in the regulation of IFN-γ on the expression of PD-1 in CD8+ T lymphocytes from COVID-19 convalescent patients." (PMID 38424104, 2024). "As such, GSK3β could serve as a candidate target for COVID-19 host-directed antiviral therapy." (PMID 36508083, 2022). "Our collective findings across multiple assays strongly demonstrate GSK3β inhibition may serve as an effective antiviral strategy for early intervention in COVID-19 and other coronavirus infections, and recommend a potent GSK3β inhibitor for further translational studies." (PMID 36508083, 2022). "Conversely, silencing of GSK3A and GSK3B drastically reduced the expression of the gene sets that characterize tissue-resident lung alveolar macrophages in COVID-19, with the concomitant silencing of GSK3A and GSK3B again showing a stronger effect." (PMID 40365863, 2025). "Increased IFN-γ in the plasma of recovered COVID-19 patients contributed to PD-1 downregulation on CD8+ T cells, which was regulated by the AKT/GSK3β signaling pathway." (PMID 38424104, 2024). "Additionally, the activation of several known tau-targeted kinases, including AMPK, glycogen synthase kinase 3 beta (GSK3β), protein kinase A (PKA), and calcium/calmodulin-dependent protein kinase II (CAMKII), was detected in the brains of COVID-19 patients." (PMID 41303587, 2025). "In addition, PBMCs from the COVID-19 recovery group were cocultured with an AKT inhibitor (GDC-0068) and a GSK3β agonist (SNP) and stimulated with T-cell activation." (PMID 38424104, 2024). "The top 5 targets were AR (degree = 93), GSK3B (degree = 70), DPP4 (degree = 52), F2 (degree = 43) and NOS3 (degree = 34), and their candidate targets may be the main targets of GGQL against COVID-19 comorbid with DM." (PMID 37933071, 2023). "In this regard, since GSK3β inhibition potentiates the profibrotic phenotype in monocyte-derived macrophage through MAFB, the pharmacological modulation of the GSK3β/MAFB axis appears as a promising strategy for macrophage reprogramming in COVID-19." (PMID 37917179, 2023).
COVID-19 (continued). "The results show that Diosmetin can highly bind with novel coronavirus-specific proteins and core gene proteins, suggesting that the effect of Diosmetin on BRCA/COVID-19 may be targeted by EGFR, AKT1, and GSK3B proteins." (PMID 36060002, 2022).
oral squamous cell carcinoma (13 papers, 2021 to 2025). "SEV miR-34a-5p from oral squamous cell carcinoma promotes EMT via Ak strain transforming (AKT)/glycogen synthase kinase-3 beta (GSK-3β)/β-catenin/SNAIL signaling." (PMID 38243280, 2024). "Loss of SFRP2 expression is also found in oral squamous cell carcinoma, and SFRP2 overexpression inhibits proliferation, cell cycle progression, and tumor growth by increasing the expression of GSK-3β and β-catenin." (PMID 34852024, 2021). "P. gingivalis also appears to stimulate IL-6 expression via the janus kinase 2/glycogen synthase kinase 3 beta/signal transducer and activator of transcription 3 (JAK2/GSK3-β/STAT3) signaling pathway, which is linked to carcinogenesis and the development of oral squamous cell carcinoma." (PMID 40806122, 2025). "In oral squamous cell carcinoma, it is related to miR-378a-3p-mediated GSK-3β/β-catenin signaling." (PMID 36996493, 2023). "Exosomal miR-34a-5p could transfer from CAFs to cancer cells, subsequently induced epithelial-mesenchymal transition (EMT) via the AKT/GSK-3β(glycogen synthase kinase 3 beta)/β-catenin pathway in oral squamous cell carcinoma (OSCC)." (PMID 35255950, 2022). "Additionally, P. gingivalis seems to promote IL-6 expression through the janus kinase 2/glycogen synthase kinase 3 beta/signal transducer and activator of transcription 3 (JAK2/GSK3-β/STAT3) pathway, which is associated with carcinogenesis and oral squamous cell carcinoma." (PMID 40805993, 2025). "For instance, in oral squamous cell carcinoma, DNMT1 knockdown induces global hypomethylation, inactivating PI3K-AKT and CDK2-Rb signaling, and cooperating with GSK3β inactivation to suppress tumorigenicity." (PMID 41381440, 2025). "In oral squamous cell carcinoma, LDOC1 inhibited microbe-induced IL-1β production by regulating the phosphoinositide 3-kinases (PI3K)/protein kinase B (Akt)/phospho-glycogen synthase kinase 3 beta (pGSK-3β) signaling pathway." (PMID 39682774, 2024). "Therefore, it is of interest to document the molecular docking analysis of proflavin with the Wnt pathway targets (GSK3β, β-catenin, and VIM)for oral squamous cell carcinoma (OSCC)." (PMID 37822816, 2023).
pancreatic ductal adenocarcinoma (12 papers, 2015 to 2025). An infiltrating adenocarcinoma that arises from the epithelial cells of the pancreas. "Overexpression of YBX1 facilitates the growth of pancreatic ductal adenocarcinoma (PDAC) through the GSK3B (glycogen synthase kinase 3 beta)/cyclin D1/cyclin E1 pathway." (PMID 38255791, 2024). "A growing body of evidence has shown that STAT3 or GSK3β activation promotes tumor development and progression, as well as gemcitabine resistance in pancreatic ductal adenocarcinoma (PDAC)." (PMID 38555280, 2024). "GSK‐3β is a serine/threonine kinase that plays a role in the development of pancreatic ductal adenocarcinoma (PDAC) by cell proliferation, survival, invasion, metastasis, and resistance to chemotherapy." (PMID 39632551, 2024). "Glycogen synthase kinase-3β (GSK-3β) is a downstream target of oncogenic KRas and can accumulate in the nucleus in pancreatic ductal adenocarcinoma (PDA)." (PMID 35646902, 2022). "We previously showed that Metavert, a dual inhibitor of glycogen synthase kinase 3-beta (GSK-3β) and histone deacetylases (HDACs) prevents pancreatic ductal adenocarcinoma (PDAC) metastasis." (PMID 41281751, 2025). "Through the GSK3B/Cyclin D1/Cyclin E1 pathway, YBX1 depletion induces apoptosis and decreases cyclin D1 and cyclin E1 protein expression, resulting in a reduction in Pancreatic Ductal Adenocarcinoma growth." (PMID 36066672, 2022). "In pancreatic ductal adenocarcinoma, ROS drived EMT by activating Akt/glycogen synthase kinase 3β (GSK3β)/Snail signaling." (PMID 33731144, 2021). "This contrasts with observations in pancreatic ductal adenocarcinoma cell lines where IKBKE mediated phosphorylation of Akt and subsequent inhibition of GSK3β regulates the nuclear retention and stabilization of c-MYC without impacting on c-MYC mRNA." (PMID 32324216, 2020). "The preferential activity of GSK3α over GSK3β in cancer cells has also been reported in pancreatic ductal adenocarcinoma (PDA), in which GSK3α, but not GSK3β, promotes activation of the canonical and non-canonical NF-κB pathways to promote cell viability and apoptosis resistance." (PMID 33339170, 2020).
prostate tumor (12 papers, 2007 to 2025). "It has been shown that aberrant activation of IGF1 signaling can either directly or via activating AKT and GSK3β axes stabilize cellular β-catenin to augment its activity for prostate tumor growth." (PMID 35902588, 2022). "SNAI2 (snail family transcriptional repressor 2) can regulate prostate tumor progress, angiogenesis, and metastasis potentially by modulating the GSK-3β/β-catenin signaling pathway." (PMID 35768705, 2022). "In addition, increased cytoplasmic GSK3β in prostate tumor samples correlated with the clinical stage and Gleason score." (PMID 27602497, 2016). "A large number of evidences point into the same direction: FAK, and its downstream signaling molecules AKT and GSK-3β, β-catenin and its upstream and downstream signaling molecules Wnt and cyclin D1, respectively, are important players in both prostate tumor development and metastasis." (PMID 20537156, 2010). "However, in mouse prostate tumors, GSK3β levels are higher than GSK3α levels, thus GSK3β may play more important roles than GSK3α." (PMID 26871944, 2016). "The PD activity of AZD5363 was determined by its ability to inhibit the phosphorylation AKT substrates (FOXO1, GSK3β) and downstream pathway biomarkers (4E-BP1 and S6), after a single oral dose in prostate tumor tissue." (PMID 26910118, 2016).
squamous cell carcinoma (12 papers, 2014 to 2024). A carcinoma arising from squamous epithelial cells. "The results also indicated that male sex, older age and squamous cell cancer (SCC) with positive GSK3β expression were associated with worse prognosis (P = 0.019, P = 0.020 and P = 0.002, respectively)." (PMID 24618715, 2014). "This evidence is reinforced by recent clinical data where cervical intra-epithelial neoplasia and squamous cell carcinoma show higher levels of p-GSK-3β Ser9 with respect to normal tissues." (PMID 32766133, 2020). "The 2012 Cancer Genome Atlas study showed that GSK3B was amplified at a frequency of 6.7% (12/178 profiled samples) in NSCLC patients with a squamous cell carcinoma histological subtype." (PMID 30969984, 2019). "In the other 10 patient samples (poorly differentiated squamous cell carcinoma), decreased GSK-3β and p-GSK-3βSer9 protein expression levels were observed, but no significant changes in p-GSK-3βTyr216 levels were identified." (PMID 29793508, 2018). "In advanced papillomas and squamous cell carcinomas, phosphorylated GSK3β(Ser9)—an inactive form of GSK3β—is markedly elevated, while the active form, phosphorylated GSK3β(Tyr216), is significantly decreased in squamous cell carcinoma tissues compared to normal tissues." (PMID 39596452, 2024). "Aberrant nuclear GSK3β may represent a potential target for the clinical treatment of human breast and squamous cell carcinoma." (PMID 31608105, 2019). "To afford comparisons with previous data identifying GSK3β and PRMT-1 as regulating the phosphorylation of DP’s C-terminus, we initially chose to use the squamous cell carcinoma cell line SCC914." (PMID 37543698, 2023). "Akt also phosphorylates Snail1 through inhibiting GSK-3β, or activates NF-κB to induce EMT in squamous cell carcinoma cells." (PMID 35183200, 2022). "In addition, in A431 epidermoid carcinoma cells and HaCaT immortalized keratinocytes both ATO and LiCl led to GSK-3β inactivation upon serine 9 phosphorylation." (PMID 28575066, 2017).
rheumatoid arthritis (11 papers, 2009 to 2024). A chronic, systemic autoimmune disorder characterized by inflammation in the synovial membranes and articular surfaces. "GSK-3β inhibitor TDZD-8 can alleviate the development of collagen II-induced rheumatoid arthritis in rats, and inhibit the proliferation of FLSs and osteolysis by inhibiting osteoclast differentiation." (PMID 39444614, 2024). "In a model of collagen-induced rheumatoid arthritis, the small molecule GSK3β inhibitor TDZD-8 reduced bone resorption." (PMID 37760805, 2023). "Inhibition to the activity of GSK3β reduced prostaglandin E2, serotonin, histamine, and other inflammatory mediators in collagen II-induced rheumatoid arthritis in rats and protected the nervous system from HIV-associated neurocognitive disorders." (PMID 33192176, 2020). "Using KO simulations, we identified NFkB, JAK1/JAK2, and ERK1/Notch1 as potential targets that could selectively suppress proinflammatory macrophages and GSK3B as a promising target that could promote anti-inflammatory macrophages in rheumatoid arthritis." (PMID 38272919, 2024). "Another study in a mouse model of rheumatoid arthritis shows that GSK-3β inhibitors suppress inflammatory responses by downregulating the NF-kB signaling pathway, along with downregulating the expression of c-Jun N-terminal kinase (JNK), c-jun, activating transcription factor (ATF) 2, and p-38." (PMID 33672232, 2021).
autism (10 papers, 2011 to 2024). Persistent deficits in social interaction and communication and interaction as well as a markedly restricted repertoire of activity and interest as well as repetitive patterns of behavior. "The primary biochemical effect of lithium is that it regulates two enzymes, glycogen synthase kinase 3-beta and phosphatidylinositol phosphatase, both of which have been linked to autism." (PMID 21651783, 2011). "In addition, affection of phosphoinositide-3-kinase/Akt/glycogen synthase kinase 3 beta (PI3K/Akt/GSK-3β) signaling may be incriminated in the pathogenic events that occur in autism." (PMID 39596986, 2024). "Coinciding with the data obtained from the present study, the results of the recent research have shone a light on the crucial role played by PI3K/Akt/GSK-3β signaling in the pathogenesis of autism." (PMID 39596986, 2024). "On the other hand, GSK-3β levels were significantly elevated in the brain in cases with autism and were proven to augment apoptosis and have a damaging effect on neuronal development." (PMID 39596986, 2024). "Our study detected p-Akt (Ser473) and p-GSK-3β (Ser9) expression in the cerebellum of the VPA-induced rat model of autism." (PMID 35318322, 2022). "Taken together, the findings from the present study demonstrated that PGRN could improve neural development via the activation of the PI3K/Akt/GSK-3β signalling pathway in a VPA-induced autism model." (PMID 35318322, 2022). "Here, we propose the repurposing of Tideglusib, an in-house non-ATP competitive GSK-3β inhibitor that is currently in clinical trials for autism and myotonic dystrophy, as a promising therapeutic strategy for ALS." (PMID 34445680, 2021). "Furthermore, the fragile X mental retardation protein (FMRP) KO mouse model of FXS exhibits increased levels of GSK-3β, whereas mice with active GSK-3α/β isozymes share some autism-related features with FMRP KO mice." (PMID 26738851, 2017). "Thus, future experiments examining GSK-3β activity in neonatal-isolated animals with or without lithium treatment will help determine whether lithium’s therapeutic effect in neonatal isolation model of autism can be attributed to its inhibition of GSK-3β." (PMID 25018711, 2014).
brain injury (10 papers, 2014 to 2025). Acute and chronic (see also brain INJURIES, CHRONIC) injuries to the brain, including the cerebral hemispheres, CEREBELLUM, and brain STEM. "In conclusion, hydrogen exerted a neuroprotective effect against neuronal apoptosis and impaired nerve regeneration through activation of miR‐21/PI3K/AKT/GSK‐3β signalling in this in vitro model of traumatic brain injury." (PMID 32108985, 2020). "Therefore, PROG is indicated to exert a protective effect on ischemic brain injury by activating the PI3K/Akt/GSK-3β pathway, which provides an experimental basis for its potential use as a drug for treating ischemic brain injury." (PMID 25187832, 2014). "In a traumatic brain injury rat model, the peak time points of Akt and GSK-3β phosphorylation are not synchronous, suggesting GSK-3β may not be phosphorylated by Akt pathway." (PMID 28400729, 2017).